LDHAL6B (lactate dehydrogenase A like 6B)
Description:
Catalyzes the interconversion of L-lactate and pyruvate with nicotinamide adenine dinucleotide NAD(+) as a coenzyme.
Synonyms: LDHAL6; LDHL; LDH6B
Tractability: PROTAC: ubiquitination databases record sites on it.
Gene: Protein-coding gene on chromosome 15 (59,206,843 to 59,208,588, forward strand). Ensembl gene ENSG00000171989.
Subcellular location (Human Protein Atlas): Cytosol
Pathways (Reactome):
Metabolism: Pyruvate metabolism
Gene Ontology:
Molecular function: protein binding; L-lactate dehydrogenase (NAD+) activity; catalytic activity; oxidoreductase activity; oxidoreductase activity, acting on the CH-OH group of donors, NAD or NADP as acceptor
Biological process: lactate metabolic process; lactate biosynthetic process from pyruvate; pyruvate catabolic process
Cellular component: cytoplasm; nucleus; mitochondrial matrix; mitochondrion; oxidoreductase complex
Genetic constraint (gnomAD): Loss-of-function variants: 2 observed, 2.18 expected, observed/expected ratio (o/e) 0.92, 90% interval 0.34 to 1.86. That is too few expected variants to judge how well the gene tolerates losing a copy. Missense variants: 523 observed, 490 expected, observed/expected ratio (o/e) 1.07, 90% interval 0.99 to 1.15. Synonymous variants: 205 observed, 175.45 expected, observed/expected ratio (o/e) 1.17, 90% interval 1.04 to 1.31.
Homologues: Orthologues: chimpanzee LDHAL6B (99% identical), macaque LDHAL6B (93% identical), rabbit LDHAL6B (82% identical), dog LDHAL6B (79% identical), rat Ldhal6b (74% identical), mouse Ldhal6b (72% identical). Paralogues in human: LDHAL6A (72% identical), LDHA (62% identical), LDHC (59% identical), LDHB (58% identical), MDH2 (22% identical).
Diseases named in the same sentence as LDHAL6B in open-access papers:
LDHAL6B is named in the same sentence as 11 diseases in open-access papers, as found by Europe PMC text mining. Sharing a sentence is not in itself a finding about the gene and the disease. The quoted sentences say what the papers report.
Obesity (2 papers, 2020 to 2023). Accumulation of substantial excess body fat. "Obesity group showed a higher mutation frequency of LDHAL6B, CPXM2, HAPLN3, and so on." (PMID 33197880, 2020).
pancreatic cancer (1 paper, 2023). "Based on survival analysis, 6 out of 32 MMRGs (LDHA, ALDH3B1, LDHAL6B, PKM, ALDH3A1, and PGAM4) in pancreatic cancer were of survival significance." (PMID 36814901, 2023).
infection (2 papers, 2017 to 2024). The state of being infected such as from the introduction of a foreign agent such as serum, vaccine, antigenic substance or organism. "While LDHAL6B was initially upregulated at 6 h of infection, its expression was undetectable later in the infection (16 h)." (PMID 28993767, 2017). "In particular, only a few glycolytic/glucanogenic genes exhibited an infection-induced change in expression (PGM2L1, LDHAL6B, ENO3, ALDH8A1, and ALDH18A1)." (PMID 28993767, 2017).
tumor (2 papers, 2016 to 2023). "Pyruvate fermentation to lactate via LDH was more complicated with LDHA and LDHAL6B being increased in tumor tissues (2.55 and 0.69 log2 fold-change, respectively), while LDHB and LDHAL6A were decreased (-2.11 and -0.24 log2 fold-change, respectively)." (PMID 27128972, 2016).
LDHAL6B also shares sentences with these, for which no sentence is quoted: COVID-19 (2 papers); asthenozoospermia (1); hepatic disease (1); Huntington disease (1); Hypertension (1); leukopenia (1); Thrombocytopenia (1).